MT-TK (mitochondrially encoded tRNA-Lys (AAA/G))
Synonyms: trnK; formerly MERRF; MTTK
Gene: Mitochondrial transfer RNA gene on chromosome MT (8,295 to 8,364, forward strand). Ensembl gene ENSG00000210156.
Gene-disease validity (ClinGen):
ClinGen rates the evidence that MT-TK causes each of these diseases.
Leigh syndrome (mitochondrial): Definitive. A progressive neurological disease defined by specific neuropathological features associating brainstem and basal ganglia lesions.
mitochondrial disease (mitochondrial): Definitive.
Diseases named in the same sentence as MT-TK in open-access papers:
MT-TK is named in the same sentence as 33 diseases in open-access papers, as found by Europe PMC text mining. Sharing a sentence is not in itself a finding about the gene and the disease. The quoted sentences say what the papers report.
MERRF (6 papers, 2017 to 2025). A mitochondrial encephalomyopathy characterized clinically by a mixed seizure disorder, myoclonus, progressive ataxia, spasticity, and a mild myopathy. "Mitochondrial MT-TK variants are most associated with myoclonic epilepsy with ragged-red fibers (MERRF) syndrome at heteroplasmy levels markedly greater than in this individual therefore, it is unlikely that this variant was explanatory for this individual’s clinical features." (PMID 37077567, 2023). "Myoclonic epilepsy with ragged-red fibers (MERRF) is a rare mitochondrial disorder primarily driven by mutations in mitochondrial DNA, particularly the m.8344A>G variant in MT-TK, and is characterized by epilepsy, myoclonus, ataxia, and other multisystemic features." (PMID 41181495, 2025).
epilepsy (4 papers, 2017 to 2025). A brain disorder characterized by episodes of abnormally increased neuronal discharge resulting in transient episodes of sensory or motor neurological dysfunction, or psychic dysfunction. "The studied patient had myoclonus, epilepsy, muscle weakness, and hearing impairment and harbored a heteroplasmic m.8315A>C variant in the MTTK gene with a mutation load ranging from 71% to >96% in tested tissues." (PMID 35886028, 2022).
MELAS (4 papers, 2012 to 2023). "Apart from the MTND gene, the mitochondrial tRNA gene could be associated with MELAS/LS overlap syndrome as well; for instance, the m.8344A>G mutation of the MTTK gene was detected in one of our patients." (PMID 34025555, 2021). "MELAS is most often caused by a 3243A-G transition in the MTTL1 gene; MERFF is caused in up to 90% of cases by an A-G mutation at nucleotide 8344 of the MTTK gene." (PMID 36862146, 2023).
myoclonic epilepsy (4 papers, 2014 to 2025). A group of epilepsy syndromes in which myoclonic seizures are a prominent feature. "Subsequently, came over others like MTTL1 and MTTK to be linked to LS: m.3243A > G MTTL1 responsible for MELAS and m.8344A > G MTTK related to Myoclonic Epilepsy with Ragged Red Fibers (MERRF)." (PMID 31996241, 2020). "Myoclonic Epilepsy with Ragged-Red Fibers (MERRF) is a rare disorder, characterized by myoclonic epilepsy and cardinal histological features of mitochondrial dysfunction, frequently caused by the m.8344A > G mt-tRNALys (MTTK) gene mutation." (PMID 24792523, 2014).
cardiomyopathy (2 papers, 2025). A disease of the heart muscle or myocardium proper. "Thirteen patients from 10 families with cardiomyopathy harbored three different mutations as follows: MTTK m.8363G > A (one family), MTND1 m.3943G > A (one family), and MTTL1 m.3243 A > G mutations (eight families)." (PMID 40382647, 2025).
mitochondrial encephalopathies (2 papers, 2021 to 2022). "Our report further expands the spectrum of MTTK variants associated with mitochondrial encephalopathies in adults." (PMID 35886028, 2022). "Our report provides solid evidence supporting the pathogenicity of a novel heteroplasmic variant, m.8315A>C, and further expands the spectrum of MTTK gene variants associated with mitochondrial encephalopathies in adults." (PMID 35886028, 2022).
Myoclonus epilepsy (2 papers, 2019 to 2023). "For myoclonus epilepsy with ragged red fibers syndrome, only the most frequent causative gene (mt‐MTTK) is listed." (PMID 31584223, 2019).
MT-TK also shares sentences with these, for which no sentence is quoted: Ataxia (4 papers); Myoclonus (4); MERRF syndrome (3); myopathy (3); tumor (3); mitochondrial myopathies (2); cataract (1); Cognitive impairment (1); deficiencies (1); dilated cardiomyopathy (1); endocrine disorders (1); Friedreich ataxia (1); infantile-onset spinocerebellar ataxia (1); Kearns-Sayre syndrome (1); Leigh syndrome (1); melanoma (1); migraines (1); mitochondrial disease (1); multiple lipomatosis (1); neuropathy (1); night blindness (1); peripheral neuropathy (1); ptosis (1); respiratory disease (1); Sengers syndrome (1); Tremor (1).